AR (androgen receptor)
Diseases named in the same sentence as AR in open-access papers (continued):
Sharing a sentence is not in itself a finding about the gene and the disease.
prostate carcinoma (continued). "For example, HNRNPL could directly regulate RNA processing, including androgen receptor RNA alternative splicing and circular RNA formation in prostate cancer." (PMID 32669100, 2020). "Our results also implicate that ERRα could be a potential therapeutic target as its inhibition could suppress the activation of AR signaling in prostate cancer cells." (PMID 32226548, 2020). "Moreover, CDK5 is also a positive regulator to cell proliferation through STAT3 activation and STAT3-mediated androgen receptor (AR) activation via the phosphorylation of STAT3 at Ser727 in prostate cancer." (PMID 33396266, 2020). "This may be due to the inherent heterogeneity of prostate cancer biology and so the use of combinations of the AR loci across genomic regions over a single gene level readout may increase the predictive performance of this assay as a molecular biomarker." (PMID 32752286, 2020). "Hence, research on prostate cancer treatments have targeted agents involved in the androgen receptor signaling axis." (PMID 35582225, 2020). "It is also imperative to investigate the associations of protein levels of AR variants, PMEPA1-b and NEDD4 in prostate cancer tissue samples, which further required to generate the PMEPA1 isoform specific antibodies to distinguish the amino acid sequence differences within N-terminus." (PMID 32842649, 2020). "In 2012, an AR inhibitor was approved by FDA for prostate cancer and yielded promising results." (PMID 32579541, 2020). "Overall, these results suggest that ERRα could play a role in activation of AR signaling in prostate cancer cells via its regulation of AKR1C3 expression." (PMID 32226548, 2020). "In this study, we tested whether and how KLF5 plays a role in the function of AR signaling in prostate cancer cells." (PMID 32245249, 2020). "We checked the expression of EMT markers, cell migration, and cell growth in PC-3 cells using AKT siRNA to assess whether the targeting AKT contributed to the anti-cancer effect in AR-independent prostate cancer cells, PC-3 cells." (PMID 32972001, 2020). "Interestingly, the inhibition of ESRPs suppressed AR-antagonist-mediated increase in the invasion of prostate cancer cells." (PMID 32820253, 2020). "Therefore, a hormone-DNA repair signaling network makes dox a plausible AR antagonist in prostate cancer." (PMID 32198885, 2020). "We used quantitative single-cell imaging of fluorescent metabolic probes, transcriptomics, proteomics, and lipidomics to perform a longitudinal analysis of the adaptive response to androgen receptor-targeted therapies (androgen deprivation and enzalutamide) in prostate cancer (PCa)." (PMID 32577235, 2020). "Therefore, there remains a gap in our understanding of AR signaling and if it can regulate the transcriptome of prostate cancer cells by altering global splicing levels." (PMID 32820253, 2020). "By contrast, as long as AR is present in prostate cancer, it typically remains an effective target for hormone-directed therapies, even in advanced stages of castration-resistant prostate cancer (CRPC), although increasingly powerful endocrine strategies are needed." (PMID 32718075, 2020). "Enzalutamide and apalutamide were eventually identified as two lead candidates for preclinical development on the grounds of in vitro evaluation of their capability of agonistic and antagonistic activity of AR signaling in a castration-resistant LNCaP/AR prostate cancer cell model." (PMID 32456317, 2020).
prostate carcinoma (continued). "However, ablation provides only temporal relief because prostate cancer cells often respond by over-expressing AR." (PMID 32283832, 2020). "Therefore, the blockage of AR signaling through androgen deprivation continues to be the mainstay treatment of advanced-stage prostate cancer." (PMID 32820253, 2020). "Since androgen receptor (AR) plays a critical role in the development and progression of prostate cancer, androgen deprivation therapy (ADT) with lowering of serum testosterone levels to castrate levels has been the mainstay of therapy for these patients for years 44-47." (PMID 31942193, 2020). "While H3R8me2s and H4R3me2s are largely considered repressive marks, they are also implicated in transcriptional activation of some genes, as has been shown for FGFR3 and eIF4E expression in colorectal cancers, and AR (androgen receptor) expression in prostate cancers." (PMID 32743345, 2020). "An alternative strategy is to deplete the AR in prostate cancer cells." (PMID 33134178, 2020). "Interestingly, these compounds are able to inhibit PSA expression in human hormone-independent prostate cancer cells, suggesting inhibition of AR signaling, a central target for the treatment of advanced prostate cancer." (PMID 32872590, 2020). "Among the many functions of the UXT, AR expression reduction in prostate cancer is comprised." (PMID 32626651, 2020). "Therefore, we are confident that a combination of AKR1C3 and AR inhibitory activity, as displayed by MF-15, is a powerful combination to combat prostate cancer." (PMID 32731472, 2020). "Our earlier work has demonstrated that ALDH1A3 highly expressed in human prostate, which had a strong correlation with primary prostate cancer luminal signature and could be a potential biomarker of AR signaling pathway." (PMID 32375698, 2020). "Evidence from AR-negative prostate cancer cells shows that DNMT1 is associated with hypermethylation of TMPRSS2 gene and low expression level of TMPRSS2." (PMID 33243086, 2020). "Improving our understanding of these AR resistance mechanisms and translating them into the next generation of AR targeting agents will be key to designing more effective therapies for advanced-stage prostate cancer." (PMID 35582225, 2020). "Androgen receptor (AR) plays an integral role in prostate cancer." (PMID 33240734, 2020). "AR and Trim24 co-activated genes are found to be high expressed in prostate cancer." (PMID 33336072, 2020). "Moreover, some G4-stabilizing agents can repress AR expression and cell growth of prostate cancer cell lines." (PMID 32477465, 2020). "The combination of USP7-inhibitors and PARP inhibitors, by affecting CCDC6 stability and HRR and accelerating AR/ARv7 turnover, may provide a novel therapeutic option in advanced prostate cancer." (PMID 32117762, 2020). "When AR is up-regulated, it promotes the development of prostate cancer." (PMID 32251318, 2020). "Androgen deprivation therapy (ADT) is a cornerstone of treatment for prostate cancer and, in recent years, androgen receptor (AR)-targeted therapies (abiraterone and enzalutamide) have both been used for the treatment of castration-resistant prostate cancer (CRPC)." (PMID 32580478, 2020). "In addition, it inhibited p300-mediated androgen receptor acetylation and acetylation-dependent prostate cancer cell proliferation." (PMID 32903408, 2020). "Via a non-canonical pathway, EZH2 methylates and activates STAT3 (Signal Transducer And Activator Of Transcription 3), acts as a co-activator for androgen receptor (AR) in castration resistant prostate cancer and enhances cellular proliferation via the E2F pathway." (PMID 33246425, 2020). "In SDC, as well as prostate cancer, the expression of FASN might be associated with the expression of AR through the endoplasmic reticulum stress response." (PMID 32103349, 2020).
prostate carcinoma (continued). "Moreover, a physical interaction between the N-terminal domain of AR and α-tubulin has been shown in prostate cancer, linking docetaxel mechanism of action with inhibition of AR nuclear translocation through regulation of α-tubulin." (PMID 33260953, 2020). "6BIO reduced both androgen receptor (AR) and AR signaling in prostate cancer cells." (PMID 32365809, 2020). "Many pre-clinical and clinical studies have highlighted the importance of AR in prostate cancer." (PMID 32714315, 2020). "For instance, calcium/calmodulin-dependent kinase kinase 2 (CAMKK2) has been identified as one of the targets of the AR in both androgen-sensitive and castrate-resistant prostate cancer cell lines since the AR was recruited to the promoter of CAMKK2 in both stages of disease." (PMID 32927797, 2020). "We first suggested that autoimmune comorbidities could have a prognostic role in prostate cancer patients treated with AR-directed therapies." (PMID 32580478, 2020). "Mechanistically, we found that epithelial splicing regulator proteins (ESRP1 and ESRP2) are the splicing factor through which AR may regulate splicing of pre-mRNA in prostate cancer cells." (PMID 32820253, 2020). "Intriguingly, AR is shown to have suppressive effects on OXPHOS in prostate cancer cells." (PMID 32932692, 2020). "Furthermore, the regulatory role of AR in gene expression has been shown to be important for the regulation of prostate cancer metastases." (PMID 33062889, 2020). "We leveraged HTA-2.0, a newer generation of microarray that interrogates junctions between exons in the transcriptome as well as the exon themselves and RNA-Seq analysis to test whether modulating AR signaling would alter ASE prostate cancer cells." (PMID 32820253, 2020). "Herein, we hypothesized that modulation of AR signaling either during prostate cancer progression or in response to treatment with AR antagonists might dysregulate the transcriptome of prostate cancer cells by modulating ASE." (PMID 32820253, 2020). "However, even with ADT, the majority of patients with recurrent prostate cancer eventually succumb to their disease as alterations of the AR pathway can result in androgen independent mechanisms that lead to the progression of prostate cancer." (PMID 32256979, 2020). "As both the established PDX and the bone metastasis organoids are derived from advanced, bone-metastatic prostate cancer, this result might reflect convergent resistance mechanisms to AR inhibition possibly evolved during tumor progression." (PMID 32656088, 2020). "Androgen receptor (AR)-mediated signaling is essential for the growth and differentiation of the normal prostate and is the primary target for androgen deprivation therapy in prostate cancer." (PMID 32927797, 2020). "Furthermore, to confirm prostate cancer origin of our circulating cells, in addition to epithelial cell origin, we co-stained CTCs for AR using an N-terminal specific AR antibody." (PMID 33062959, 2020). "Interestingly, activated AR molecules both enhance and suppress the expression of genes involved in prostate cancer progression." (PMID 32820253, 2020). "Another opportunity that might merit further investigation would be to better define the role of SHBG in the efficiency and selectivity of imaging AR in prostate cancers, which proved to be a challenging problem to address in preclinical models." (PMID 32718075, 2020). "Evidence also suggests that men with TMPRSS2:ERG positive tumors may have longer prostate cancer survival after androgen-deprivation therapy (ADT) and this is further discussed in the section of AR gene polymorphisms." (PMID 33243086, 2020). "The androgen receptor (AR) plays a leading role in the control of prostate cancer (PCa) growth." (PMID 32650419, 2020). "In addition, KRAS and androgen receptor synergistically simulate tumor-propagating cells in prostate cancer." (PMID 32101536, 2020).
prostate carcinoma (continued). "Identification of novel signaling molecules/ pathways that may play a critical role in aberrant AR activation in prostate, is of utmost importance for developing new treatment strategies and drug targets for patients with advanced prostate cancer." (PMID 32881870, 2020). "The androgen receptor (AR) is a major driver of prostate cancer development and progression." (PMID 32477465, 2020). "In prostate cancers, 40-80% of tumors harbor a gene fusion between the androgen receptor (AR)-responsive transmembrane protease serine 2 (TMPRSS2) gene and E26 transformation-specific (ETS) family transcription factor, most often the oncogene ETS-related gene (ERG)." (PMID 33135109, 2020). "Currently, androgen receptor antagonists are used to treat benign prostatic hyperplasia, prostate cancer, alopecia, hypersexuality, precocious puberty, and transgender transition in men, whereas in women, these drugs are used to treat acne, hirsutism, hyperandrogenism, and amenorrhea." (PMID 32223745, 2020). "PTS33, a sodium derivative of CT, could selectively inhibit prostate cancer cells growth by inhibiting the expression of androgen receptor (AR) protein and blocking the expression of AR-regulated genes." (PMID 32265690, 2020). "In addition, AR is a well-recognized biomarker to predict prognosis in prostate cancer, and acquired ligand-independent activity of AR is a predictor for drug-resistant prostate cancer." (PMID 31896509, 2020). "Overexpressed c-Jun mediates, then, an inhibitory effect on the function of AR, further supporting the idea that this polyphenol might potentially be useful in prostate cancer treatment." (PMID 30832393, 2019). "According to these observations it was suggested that combinatorial targeting of NOTCH and AR signaling may have a therapeutic potential in advanced prostate cancers bearing ERG rearrangements." (PMID 31366128, 2019). "Androgen receptor (AR) plays important roles in tumorigenesis of prostate cancer." (PMID 31295943, 2019). "Androgen receptor inhibition has also been hypothesized to be a more effective treatment for prostate cancer patients with HRD because of the role that androgen receptor signaling plays in the regulation of DNA repair." (PMID 31915536, 2019). "ESRP2 is a direct target for AR regulation in prostate cancer cells." (PMID 31478829, 2019). "GREB1 knockdown also inhibits the proliferation of AR-positive prostate cancer cells." (PMID 31462641, 2019). "When prostate cancer cells are adapted to a low androgen environment, AR and WNT/β-catenin signaling may reinforce each other to promote androgen-independent growth and progression." (PMID 31387608, 2019). "Previously, we demonstrated that androgen/AR signaling increases prostate cancer cell proliferation, while simultaneously inhibiting cancer cell migration, which is induced by the activation of several C-C motif ligand (CCL)-receptor (CCR) axes downstream or upstream of androgen/AR signaling." (PMID 30871130, 2019). "Consequently, Prx1 acts to facilitate tumor progression by increasing the transactivation of AR in prostate cancer." (PMID 31185618, 2019). "In addition, in contrast to bicalutamide, apalutamide lacks significant AR agonist activity in preclinical models of CRPC and is unable to induce AR nuclear translocation and DNA binding in prostate cancer cells." (PMID 31446511, 2019). "Thus, under hypoxia, perhaps AR contributes to global glycolysis activation at least in prostate cancer cells." (PMID 31600993, 2019). "In this study, we tested whether and how ERβ and ZFHX3 coordinate to function in AR-positive prostate cancer cells." (PMID 30979864, 2019). "In combination with ADT, the CCL21-CCR7 axis may, therefore, prove a superior target compared with single androgen/AR signaling-targeted therapy for treatment of patients with prostate cancer and lymph node metastasis." (PMID 30871130, 2019).
prostate carcinoma (continued). "Interestingly, an AR antagonist (bicalutamide) was found to upregulate prosurvival autophagy in LNCaP prostate cancer cells." (PMID 30621351, 2019). "In both androgen-dependent and castration-resistant prostate cancer cells, β-arr1 enhances the binding of androgen receptor (AR) to androgen response elements, favoring cell proliferation, growth, and invasion, as well as in vivo tumor formation, local invasion, and distant metastasis." (PMID 30837880, 2019). "Using prostate cancer as an exemplar, we showed that acquisition of pluripotent master regulators drove castration resistance independent from conventional AR related signalling and uncovered the TH pathway as a new treatment target for castration-resistant disease." (PMID 30742096, 2019). "Interestingly, a previous report found that hnRNPK is critical suppressor of AR translation, and the expression of hnRNPK and AR is negatively correlated in prostate cancer." (PMID 31221168, 2019). "In conclusion, the integration of different biomarker strategies, including genomics, with plasma AR status in prostate cancer, could substantially improve prognostication and stratification of these patients." (PMID 31689899, 2019). "In PTEN-deficient prostate cancers, AKT signaling may be activated upon suppression of androgen receptor signaling." (PMID 30773595, 2019). "Interestingly, assays performed in both early and late stage of prostate cancer cells have shown that these compounds can prevent AR-dependent gene expression as well as the proliferation of prostate cancer cells stimulated by androgens." (PMID 30717249, 2019). "Furthermore, EGCG reduced AR expression by 20% and 30% at the mRNA and protein levels, respectively, in androgen-dependent prostate cancer cells." (PMID 30823649, 2019). "In androgen-dependent prostate cancer, increased Src-1 expression is correlated with lymph node metastasis, and depletion of Src-1 in androgen-dependent prostate cancer cell line LNCaP represses AR-dependent cellular proliferation and activation of AR target genes." (PMID 30973923, 2019). "For example, semi-selective KDM4 inhibitors that abrogate KDM4B activity have been shown to be efficacious in inhibiting AR-signalling and growth in prostate cancer cells and to be effective in inhibiting the growth of MYC-driven neuroblastomas and breast cancer stem-like cells." (PMID 31390833, 2019). "In addition, several important reports have demonstrated that the androgen receptor (AR) splicing pathway is a key driver for prostate cancer progression." (PMID 30939845, 2019). "It suggests that Roscovitine prevents AR translocation in prostate cancer cells." (PMID 31395805, 2019). "The role of PARP1 in regulating AR function in prostate cancer and the potential synergy between PARPi and AR signaling inhibitor was tested in another phase II randomized, double-blind study comparing olaparib and abiraterone versus placebo and abiraterone in mCRPC." (PMID 31404966, 2019). "Thus, CDK5 plays a crucial role in the growth of prostate cancer cells, and AR regulation is one of the important pathways." (PMID 31395805, 2019). "It is well known that the androgen/AR signaling pathway is crucial for prostate cancer development." (PMID 31871879, 2019). "Prostate cancer (PCa) is driven by the androgen receptor (AR)‐signaling axis." (PMID 30776192, 2019). "Thus, activated PKA, a phenomenon frequently observed in advanced prostate cancer, potentiates and allows the AR activation event in the presence of low androgen concentration." (PMID 31366128, 2019). "In addition, WPMY1-AR stromal cells and LNCaP prostate cancer cells were diluted 1:100 in brain extract to serve as positive controls for AR." (PMID 31350272, 2019).